PTPRN2 (protein tyrosine phosphatase receptor type N2)
Diseases named in the same sentence as PTPRN2 in open-access papers (continued):
Sharing a sentence is not in itself a finding about the gene and the disease.
Insulin resistance (6 papers, 2017 to 2025). Increased resistance towards insulin, that is, diminished effectiveness of insulin in reducing blood glucose levels. "While PTPRN2 has been extensively characterized in the context of insulin resistance, its involvement in lipid metabolism remains sparsely explored." (PMID 41010281, 2025). "In the present study, PTPRN2 is decreased in PD relative to HC, which may contribute to the link between insulin resistance and PD observed in certain patients." (PMID 32051502, 2020). "These genes have been involved in insulin resistance and secretion (ATM, PTPRN2, PSMD10, and NSF), adipogenesis (SLC25A24 and PAX8), inflammatory processes (TNFRSF8 and SLIT3), and mitochondrial processes (PM20D1 and LCLAT1)." (PMID 36535927, 2022).
depression (5 papers, 2021 to 2026). "The PTPRN2 gene coding for the Protein Tyrosine Phosphatase Receptor Type N2 has been found to be associated with increased Hospital Anxiety and Depression Scale – Anxiety (HADS-A) scores in a recent GWAS." (PMID 40281224, 2025). "Hypermethylated cytosine sites of PTPRN2 have been linked to depression in trauma survivors." (PMID 38328521, 2023). "Our results showed significant causal genetic evidence for injury-associated DNAm changes at cg24526596 (DLGAP2), cg00157656 (ERICH1), cg12317217 (PCDHA2), and cg12661624 (PTPRN2) on depression onset." (PMID 41995537, 2026). "The present study provided genetic evidence supporting the causal role of DNAm in the onset of depression or PTSD after injury and identified DLGAP2, ERICH1, PCDHA2, and PTPRN2 as the candidate genes worthy of further exploratory investigation." (PMID 41995537, 2026). "Additionally, four genes HELZ2, PTPRN2, GATA2, and ZNF624 were differentially expressed between depression cases and health controls." (PMID 34341332, 2021).
prostate carcinoma (5 papers, 2005 to 2024). A carcinoma that arises from epithelial cells of the prostate gland. "Our data confirmed that the treatment of prostate cancer cells with ENZA enhances the effect of radiation through down-regulation of NKX3-1, ZMIZ1, SPDEF and PDE9A genes and up-regulation of LAT, PTPRN2 and OSBPL10 genes in LNCaP cells, as well as up-regulation of CYP1B1 genes in C4-2 cells." (PMID 31221986, 2019).
lung carcinoma (4 papers, 2009 to 2019). "The Ptprn2 locus is reported to be hypermethylated in lung cancer while Pkhd1 (polycystic kidney and hepatic disease 1) is associated with polycystic kidney and hepatic disease." (PMID 19812696, 2009).
Anxiety (3 papers, 2023 to 2025). Intense feelings of nervousness, tension, or panic often arise in response to interpersonal stresses. "However, there was a strong association between clinical anxiety and PTPRN2 (rs3857647), which is required for noradrenaline, dopamine, and serotonin accumulation in the brain." (PMID 38328521, 2023). "There was an association between anxiety levels (HADS-A scores) and genes involved in the activity of excitatory neurotransmitters: PTPRN2 (rs3857647), DLGAP4 (rs8114927), and STK24 (rs9517326)." (PMID 38328521, 2023). "Knockout of the gene PTPRN2 in mice increases anxiety-like behavior." (PMID 40560842, 2025). "The detection of PTPRN2, which is required for the accumulation of noradrenaline, dopamine, and serotonin in the brain, adds to the evidence that monoamine neurotransmitters play a role in the development of anxiety." (PMID 38328521, 2023).
asthma (3 papers, 2020 to 2022). "Methylation in PTPRN2 is associated with childhood asthma and chronical obstruction pulmonary disease in adulthood, and it is also related to residential proximity to major roadways in the placenta samples of pregnant women." (PMID 35163587, 2022).
autoimmune disease (3 papers, 2018 to 2020). A disorder resulting from loss of function or tissue destruction of an organ or multiple organs, arising from humoral or cellular immune responses of the individual to their own tissue constituents. "Especially, the differential methylation of PTPRN2 in naive CD4+ T cell was associated with autoimmune disease, which suggested its role for immune response." (PMID 30890718, 2019).
colon cancer (3 papers, 2009 to 2024). "Cell and animal experiments show that HOXD13 can bind to PTPRN2 (Protein tyrosine phosphatase, receptor type N2) promoter and up-regulate its expression, thus promoting the development of colon cancer." (PMID 38336605, 2024). "Clinical data and in vitro tests have shown that HODX13 promotes the progression of colon cancer through PTPRN2." (PMID 34272834, 2021). "Then, we used Transwell, wound healing, and colony formation tests to detect the effects of different levels of PTPRN2 on the phenotype of colon cancer cells." (PMID 34272834, 2021). "The knockdown of PTPRN2 expression in colon cancer cells can inhibit cell migration, invasion, and clonal formation." (PMID 34272834, 2021). "This research also explains the transcriptional regulatory relationship between HOXD13 and protein tyrosine phosphatase receptor type N2 (PTPRN2) and their mechanisms in the malignant progression of colon cancer." (PMID 34272834, 2021). "Next, we used IHC to detect the expression of PTPRN2 in colon cancer patients and observed that the expression of PTPRN2 in the colon was higher than that in adjacent tissues." (PMID 34272834, 2021). "Here, we first determined whether the function of PTPRN2 in colon cancer is in line with our speculation." (PMID 34272834, 2021). "Overall, HOXD13 promotes the malignant progression of colon cancer through PTPRN2." (PMID 34272834, 2021). "The promotion of HOXD13 in colon cancer is partly achieved by PTPRN2." (PMID 34272834, 2021). "We discovered that PTPRN2 is highly expressed in colon cancer and predicts a poor prognosis." (PMID 34272834, 2021). "We conducted a rescue experiment to further confirm whether PTPRN2 mediates the tumor‐promoting effect of HOXD13 in colon cancer." (PMID 34272834, 2021).
glioblastoma (3 papers, 2016 to 2023). The most malignant astrocytic tumor (WHO grade IV). "PTPRN2 has been reported to be significant hypermethylated in squamous cell lung cancer and glioblastoma." (PMID 28514750, 2017). "The hypermethylation of the PTPRN2 promoter region in glioblastomas and lung adenocarcinomas suggests tumor suppressor roles." (PMID 27586084, 2016). "Hypermethylation of the PTPRN2 promoter region in glioblastomas suggests tumor suppressor roles." (PMID 36650953, 2023). "Interestingly, a similar epigenetic signature for AJAP1, ADARB2 and PTPRN2 has been previously reported in glioblastoma." (PMID 28514750, 2017). "Notably, seven PTP genes (DUSP26, MTMR4, PTEN, PTPRM, PTPRN2, PTPRT and PTPRZ1) were differentially expressed between grade II-III gliomas and (grade IV) glioblastomas." (PMID 27586084, 2016).
hearing loss (3 papers, 2021 to 2024). "Behavioral pathologies are also mirrored in IA-2β deficient mice, and this connection with hearing defects is corroborated by the identification of rs10081191 in PTPRN2 being associated with noise-induced hearing loss in a Chinese cohort." (PMID 36755664, 2022). "Thus larger population samples and more in-depth experimental studies are needed to confirm the mechanism of PTPRN2 in hearing loss." (PMID 38212800, 2024). "Recently, PTPRN2 genomic duplication has been shown to be linked to severe bilateral hearing loss." (PMID 33242228, 2021). "Expression levels for the gene indeed matter, given the reports that the detection of CNVs and RNA-seq data connect PTPRN2 with neurodevelopmental disorders including autism, attention deficit hyperactivity disorder and syndromes involving hearing impairments." (PMID 36755664, 2022).
Infertility (3 papers, 2023 to 2024). "Simultaneous knockout of the neuroendocrine marker genes Ptprn and Ptprn2, which encode the protein tyrosine phosphatase receptors N and N2, causes infertility in female mice while males are fertile." (PMID 36611058, 2023). "Moreover, a case–control study published in 2019 identified 38 candidate genes, including PTPRN2, as being important for spermatogenesis and fertility, which were differentially methylated and/or exhibited a high testes expression between infertility cases and controls." (PMID 37628668, 2023).
lung squamous cell carcinomas (3 papers, 2011 to 2017). "We have found PTPRN2 to be frequently methylated in adenocarcinoma and squamous cell cancer of the lung, in at least two independent sample sets for both histological subtypes (and unpublished results)." (PMID 21731750, 2011). "Frequent methylation of PTPRN2 and ZNF577 were reported in lung squamous cell carcinomas." (PMID 27926516, 2017).
type 2 diabetes (3 papers, 2016 to 2021). "Interestingly in the present study, the lead SNP rs2091718 in the PTPRN2 gene has been significantly associated with type 2 diabetes prevalence." (PMID 35052758, 2021). "Additional adjustment of the model for type 2 diabetes did not change the level of significance for the PTPRN2 gene (p = 3.94 × 10−5)." (PMID 35052758, 2021).
atherosclerosis (2 papers, 2022 to 2023). A disease characterized by the build-up of fatty material and calcium deposition in the arterial wall resulting in partial or complete occlusion of the arterial lumen. "Variations in the PTPRN2 gene have been associated with calcified atherosclerotic plaque, a subclinical marker of atherosclerosis, in human peripheral arteries, and familial stroke." (PMID 38132326, 2023). "Top DMPs were annotated to the PTPRN2, SKIL, and KCNT1 genes, which have been reported in relation to cardiometabolic risk factors, atherosclerosis, and sodium-potassium handling." (PMID 36457109, 2022). "For instance, hypermethylation in the PTPRN2 gene has been associated with metabolic syndrome in African American population, and hypermethylation of the SKIL gene has been associated with atherosclerosis." (PMID 36457109, 2022).
female infertility (2 papers, 2021). Diminished or absent ability of a female to achieve conception. "Importantly, double knockout of PTPRN2/phogrin and the closely-related Ptprn (IA-2) gene leads to defective FSH and LH production and female infertility, implying an important role in the anterior pituitary." (PMID 33492421, 2021).
glioma (2 papers, 2016 to 2023). A benign or malignant brain and spinal cord tumor that arises from glial cells (astrocytes, oligodendrocytes, ependymal cells). "PTPRN2 was identified as a new regulator in the progression of glioma by comprehensive protein tyrosine phosphatase mRNA profiling." (PMID 36650953, 2023). "Together with PTPs that impinge upon cellular contacts (DUSP26, PTPRZ1) and phospholipid signaling (MTMR4, PTEN and PTPRN2) they provide novel cues to explore and design glioma treatment options." (PMID 27586084, 2016). "The biological impact of PTPRN2 on tumors may thus be context dependent, and the role of PTPRN2 in glioma biology needs further investigation." (PMID 36650953, 2023). "Our findings suggest that HIC2 represents a tumor suppressor gene and prognostic biomarker for glioma progression and that overexpression of HIC2 inhibits the proliferation of glioma in vitro and in vivo by interacting with RNF44 and PTPRN2." (PMID 36650953, 2023). "The tumor biological impact of PTPRN2 and MTMR4 may thus be context-dependent, and how these PTPs feed into glioma biology needs further investigation." (PMID 27586084, 2016). "We additionally identified PTPRT, DUSP26, PTPRN2 and MTMR4 in our screen for glioma-relevant PTPs." (PMID 27586084, 2016). "However, another study found that PTPRN2 did not correlate with glioma patient survival." (PMID 36650953, 2023).
joint disease (2 papers, 2019 to 2021). "Changes in the methylation levels of genes associated with skin/joint disease (MBP, OSBPL5, SNORD115, and HCG26) and joint disease (IL22, ELF5, PPP2R2D, PTPRN2, and HCG26) were found." (PMID 33869291, 2021). "Biological inference prioritized notable DMRs associated with skin disease (SIGLEC14, JAM3, PCOLCE, RXRB), skin and/or joint disease (MBP, OSBPL5, SNORD115, HCG26), and joint disease (IL22, ELF5, PPP2R2D, PTPRN2, HCG26)." (PMID 30779748, 2019). "Although few DMRs exceeded a 10% change in methylation, it is noteworthy that many of those which did play roles in the pathogenesis of skin disease (SIGLEC14, JAM3, PCOLCE, RXRB, ELF5, IL22), joint disease (MBP, HCG26, IL22, PPP2R2D, PTPRN2) or are known to be imprinted (OSBPL5, SNORD115)." (PMID 30779748, 2019).
leiomyosarcoma (2 papers, 2021). An uncommon, aggressive malignant smooth muscle neoplasm, usually occurring in post-menopausal women. "DNA methylation of DAXX and receptor-type tyrosine-protein phosphatase N2 (PTPRN2) has been found in patients with leiomyosarcoma." (PMID 35008848, 2021).
lupus (2 papers, 2015 to 2024). "Epigenetic studies confirm lower methylation levels of PTPRN2 in African-American lupus patients compared with those of European-American descent, which suggests its role for immune response." (PMID 38336605, 2024). "We then confirmed that these genes, such as IL32, CD226, CDKN1A, and PTPRN2 were similarly hypomethylated in lupus patients of African-American compared to European-American descent." (PMID 26609326, 2015).
ovarian carcinoma (2 papers, 2015 to 2021). A malignant neoplasm originating from the surface ovarian epithelium. "According to the COSMIC database, PTPRN2 copy number variations are observed in several cancers (for instance, in 46% of ovarian cancers) and in 73% of central neural system disorder tissues." (PMID 25958397, 2015).
sarcoma (2 papers, 2019 to 2021). A usually aggressive malignant neoplasm of the soft tissue or bone. "Differentially methylated regions and genes were detected, not been previously implicated in sarcoma progression, including at PTPRN2 and DAXX in LMS, WT1-AS and TNXB in SS, VENTX and NTRK3 in pleomorphic RMS and MEST and the C14MC / miR-379/miR-656 in MFS." (PMID 33436720, 2021).
aneurysm (1 paper, 2021). Bulging or ballooning in an area of an artery secondary to arterial wall weakening. "Upon studying these genes for a possible role in MFS, four genes (FNBP1, EHBP1, SDK1, and PTPRN2) were found to be involved in cytoskeletal actin dynamics, which regulates cell-adhesion and cellular uptake or secretion, which is altered in MFS cells, and thought to play a role in aneurysm formation." (PMID 34895303, 2021).
Autoimmunity (1 paper, 2014). The occurrence of an immune reaction against the organism's own cells or tissues. "An accumulation of somatic mutations in PTPRN2 (without autoimmunity) could lead to glucose intolerance." (PMID 24988487, 2014).
Azoospermia (1 paper, 2023). Absence of any measurable level of sperm,whereby spermatozoa cannot be observed even after centrifugation of the semen pellet. "Another study showed that the PTPRN2 gene showed highly differential methylation differences between severe oligospermia and obstructive azoospermia." (PMID 37628668, 2023).
colorectal cancer (1 paper, 2025). A primary or metastatic malignant neoplasm that affects the colon or rectum. "Moreover, PTPRN2 plays a role in vesicle-mediated secretory processes, and has been associated with progression and as a methylation biomarker of poor survival in colorectal cancer." (PMID 41226303, 2025).
coronary artery calcification (1 paper, 2023). Calcification of the coronary artery, used as a measure of coronary atherosclerosis, a risk factor for myocardial infarction. "Multi-Ethnic Study of Atherosclerosis (MESA) similarly demonstrated PTPRN2 expression is associated with coronary artery calcification and carotid plaque score." (PMID 37533055, 2023).
coronary heart disease (1 paper, 2023). "The Cohorts for Heart and Aging Genetic Epidemiology (CHARGE) Consortium has performed the largest prospective EWAS of coronary heart disease to date and reported associations with DNAm in PTPRN2 and MAD1L1." (PMID 37533055, 2023).
COVID-19 (1 paper, 2021). A disease caused by infection with severe acute respiratory syndrome coronavirus 2. "These two genes (TSHR and PTPRN2) did not increase in the mild COVID-19 and hence they were associated with more severe infection." (PMID 34276672, 2021). "In whole blood study, seven autoantigens were upregulated in blood of severe COVID-19 patients (MPO, PRTN3, PADI4, IFIH1, TRIM21, PTPRN2, and TSHR), while four autoantigens (MPO, PRTN3, IFIH1, and PADI4) were increased in blood of mild patients." (PMID 34276672, 2021). "Comparison of COVID-19 blood transcriptomic with IAV and RSV revealed that MPO, PRTN3, and PADI4 were selectively upregulated in coronavirus infections, SARS-CoV-1 and SARS-CoV-2, while TSHR and PTPRN2 autoantigens were distinctive to SARS-CoV-2 infection." (PMID 34276672, 2021).
Duane retraction syndrome (1 paper, 2021). Duane retraction syndrome (DRS) is a congenital form of strabismus characterized by horizontal eye movement limitation, globe retraction and palpebral fissure narrowing in attempted adduction. "Interestingly, the PTPRN2 gene mutation has been shown to cause bilateral Duane retraction syndrome with severe bilateral hearing loss." (PMID 33242228, 2021).
gestational diabetes (1 paper, 2022). Carbohydrate intolerance first diagnosed during pregnancy. "Differential methylation in PTPRN2 in whole blood has been associated with gestational diabetes, with childhood adiposity as well as childhood obesity." (PMID 35500004, 2022).
Hypertension (1 paper, 2016). The presence of chronic increased pressure in the systemic arterial system. "Of those, 28 genes had more than 5 var-HpaII sites, and several of those have been reported the association with PE (PTPRN2, KCNMA1, and NFATC1), hypertension (SDK1), and placental development (SALL3)." (PMID 27293492, 2016).
leukemia (1 paper, 2021). A malignant (clonal) hematologic disorder, involving hematopoietic stem cells and characterized by the presence of primitive or atypical myeloid or lymphoid cells in the bone marrow and the blood. "We evaluated the nuclear location of the chromosomal region surrounding MNX1 in the leukemia K562 cell line by FISH, and assessed the transcriptional activity of genes mapping in same region (i.e., LMBR1, NOM1, MNX1, UBE3C, and PTPRN2) by qRT-PCR." (PMID 33652823, 2021).
myocardial infarction (1 paper, 2021). Gross necrosis of the myocardium, as a result of interruption of the blood supply to the area, as in coronary thrombosis. "DNA methylation in placental tissue at sites encoding PTPRN2 and CASZ1 are associated with cardiometabolic disease in adulthood, and DNA methylation in blood leukocytes at the location of the PTPRN2 gene is associated with future myocardial infarction." (PMID 34895303, 2021).
narcolepsy (1 paper, 2023). A sleep disorder characterized by a tendency for excessive sleepiness during the day which occurs even after adequate sleep in the nighttime. "Also, ITIH3 and PTPRN2 are proteins found in this study and have also been reported in proteomics profiling in narcolepsy rat models, as well as some other gene expression studies." (PMID 36979356, 2023).
neuroendocrine tumors (1 paper, 2011). "Eight genes (CHGA, CPE, ENO2, INSM1, PTPRN2, SERPINA10, and SLC18A1/2) that have been previously identified as markers of neuroendocrine tumors were confirmed in this study to be altered." (PMID 21853033, 2011).
pancreatic cancers (1 paper, 2021). "PTPRN2 is overexpressed in a series of tumors, including breast and pancreatic cancers." (PMID 34272834, 2021).
polycystic kidney and hepatic disease 1 (1 paper, 2009). "Additional members of this network are Ptprn2 (protein tyrosine phosphatase, receptor type, N polypeptide 2) and Pkhd1 (polycystic kidney and hepatic disease 1), which act i.e. as signaling molecule involved in cell growth, differentiation, mitotic cycle, and oncogenic transformation." (PMID 19812696, 2009).